MIR580 (microRNA 580)
Synonyms: hsa-mir-580; MIRN580
Gene: MicroRNA gene on chromosome 5 (36,147,892 to 36,147,988, reverse strand). Ensembl gene ENSG00000207756.
Gene Ontology:
Biological process: miRNA-mediated post-transcriptional gene silencing
Cellular component: RISC complex